CD4 (CD4 molecule)
Diseases named in the same sentence as CD4 in open-access papers (continued):
Sharing a sentence is not in itself a finding about the gene and the disease.
infection (continued). "A strong T helper 1 response is characteristic of S. Typhimurium infection in the mouse, with a large expansion in numbers of activated IFNγ-secreting CD4+- and CD8+-T cells in the blood, though this response takes a week to develop during primary infection." (PMID 21048923, 2010). "As infection with HIV destroys the CD4 cells and the immunologic system attempts to eliminate the virus, the CD8 cells rise and CD4 cells decrease." (PMID 20169116, 2010). "In active TB, macrophages release pro-inflammatory cytokines (IL-1, IL-6, TNF-α) in response to mycobacterial proteins and glycolipids, resulting in CD4 and CD8 T lymphocyte recruitment and activation at the site of infection and systemically." (PMID 20179751, 2010). "In contrast, by stimulating this tremendous naïve and central memory CD4+ T cell repertoire that is programmed to generate additional CCR5 expressing targets, the virus creates new sources of infection and avoids the consequences of target cell depletion." (PMID 20569472, 2010). "Several studies of mucosal pathogenesis in HIV-1 infected humans and SIV infected macaques have focused on depletion of CD4+ LPL, as they are a primary target of infection." (PMID 20085648, 2010). "Expression of Tax in Jurkat cells boosted infection by about 5-fold for both HTLV-1 and HIV-1 VLPs in Jurkat-Raji/CD4 cocultures." (PMID 20195464, 2010). "Treatment of purified CD4+ T cells with EFV reduced significantly the percentage of DCIR-expressing cells, thus indicating that productive infection with HIV-1 is mandatory to lead to DCIR expression." (PMID 21085612, 2010). "Infection on NP2/CD4/CXCR4 is 60X (MCN) and 200X (MCR) greater than on the restricted HeLa/CD4 cells." (PMID 20929586, 2010). "Since 1084i Env is R5 tropic, we then tested the replication dynamics of subtype C-based viruses in U87.CD4.CCR5 cells, whereas the infection with NL4-3 and NL4-3-based chimeric virus was performed in Sup-T1 cells." (PMID 20939905, 2010). "Our findings demonstrate that infection of BALB/c mice with HSV-1 KOS strain by corneal scarification resulted in upregulation of BTLA expression in the infected corneas and in CD4+ T cells from murine peripheral blood." (PMID 21042564, 2010). "Consistently, infection of mice for 24 h with Ye resulted in the increased production of the proinflammatory cytokines IL-12 and TNF by CD4+ and CD4−CD8α− DCs compared to PBS-treated mice." (PMID 21124820, 2010). "This was achieved and we were able to block infection in the standard TZM-bl assay for lentiviral infection by either blocking the host cell co-receptor (via MIP1α display) or the virus itself, via CD4 display." (PMID 20442778, 2010). "The role of both naturally occurring CD4+CD25+ Tregs and IL-10-secreting Tregs in infection has been the subject of several recent excellent reviews." (PMID 20064232, 2010). "When a comparison was done at an earlier stage of HIV-1 infection (CD4 counts > 200), CXCR4 use was more frequent among patients with subtype D infection, probably due to an earlier coreceptor switch than in patients infected with subtype A." (PMID 20307309, 2010). "Anti-mouse CD4 and anti-mouse CD8 depleting antibodies were administered beginning day 31 post-infection." (PMID 20714351, 2010). "By contrast, they propose that immortalized CD4+ T cell lines are more permissive for HIV-1 fusion, and so endocytosis is less dominant and productive infection more prominent." (PMID 21994681, 2010). "We recently reported that palmitic acid (PA) is a novel and efficient CD4 fusion inhibitor to HIV-1 entry and infection." (PMID 20730055, 2010). "NK cells and CD4 and CD8 T cells play important roles in the recovery from a primary ECTV infection." (PMID 20300179, 2010). "Both immunotoxins inhibited spreading infection of all the HIV-1 primary isolates tested (clade B), again with 3B3-PE showing greater potency than CD4-PE." (PMID 20548940, 2010).
infection (continued). "Virus or virus-infected cells then reach the draining lymph nodes, where activated CD4+CCR5+ T cells are encountered and represent targets for further infection." (PMID 20569472, 2010). "The levels of both CD4+ and CD8+ T cells normalized to the pre-infection levels by 12 weeks post-infection." (PMID 20824205, 2010). "Additional phenotypic characterization revealed that the percent activated (CD44hiCD62Llo) CD4+ and CD8+ T cells both increased sharply beginning week 3, and were sustained at high levels through week 7 after infection." (PMID 20714351, 2010). "Two-colour flow cytometry of splenic CD3 and CD19 T- and B-lymphocytes, CD4 and CD8 T-lymphocytes, and γδ T-lymphocytes in mice infected with S. Enteritidis 5 days post-infection." (PMID 20226037, 2010). "Masking the CD4 and V3 loop area by mHSA was also efficient for the blockade of CCR5-specific infection, but 3 times higher levels were necessary compared to the neutralization of CXCR4-viruses." (PMID 20525179, 2010). "In the acute phase of infection with feline immunodeficiency virus (FIV), the virus targets activated CD4+ T cells by utilising CD134 (OX40) as a primary attachment receptor and CXCR4 as a co-receptor." (PMID 20420700, 2010). "IL-17 is also produced in vivo by CD4+, CD8+ and NK cells from BALB/c mice on the early acute phase of infection." (PMID 20169058, 2010). "The contact of HTLV-1-infected DC with CD4+ T cells upregulates NRP-1 and HSPG within an hour followed by transmission of HTLV-1 to T cells and productive infection." (PMID 21114861, 2010). "These included reduced percentages of circulating memory CD4+ T-cells in alcohol-treated animals 7 days after infection, as well as increased levels of CCR5-expressing monocytes 12 days after infection in alcohol-treated animals compared with controls." (PMID 23584062, 2010). "The interaction between HSV-2 and epithelial cells triggers cytokine and chemokine secretion to recruit dendritic cells (DCs), macrophages, and CD4+ and CD8+ T cells to control infection and symptomatic reactivation." (PMID 20011586, 2009). "On the other hand, JHD−/− mice, which lack B cells but have functional CD4 and CD8 T cells, often survive CVS-F3 infection over extended periods despite being unable to clear virus from CNS tissues and exhibiting neurological symptoms." (PMID 19806203, 2009). "Compared to the DMSO treatment control, both TXE and VAD treatment showed significant lower Luc activities in both U87.CD4.CXCR4 and U87.CD4.CCR5 cells, indicating that they blocked HIV-1 89.6 infection." (PMID 19656383, 2009). "CD4+CD25+ T cells were recently shown to be increased in adult measles patients, suggesting their potential role during infection, although this finding has been contradicted by the others." (PMID 19319188, 2009). "During primary infection, we observed a parallel decrease in vRNA levels in the GALT and plasma, probably due to the progressive depletion of activated memory CD4+ T cells during primary infection in this tissue." (PMID 19930655, 2009). "Infection of Cryptosporidium, I. belli and S. stercoralis was significantly higher among HIV positive subjects, particularly in those with lower CD4 T-cell counts." (PMID 19765310, 2009). "Our results show that CD4 and CD8 T cells directed to epitopes in the same antigen differ both in their kinetics and functional characteristics throughout an infection with M. tuberculosis." (PMID 19529765, 2009). "In the first stages of infection (the focus of the present study), it is clear that both BCG and Mtb are controlled by CD4 T cells." (PMID 20011592, 2009). "In the most well-characterized pathways, infection upregulates expression of ligand for receptor activator of NF-κB (RANK-L) on specific antigen-activated B and CD4+ T lymphocytes." (PMID 19859584, 2009).
infection (continued). "Uninfected and PLV single infected cats overlap in the projection on the first two LDA axes; both have higher levels of CD4 and CD25 cells and neutrophils compared to cats with single and dual FIVC infection." (PMID 19806226, 2009). "FIVC single infections separate from uninfected cats and single PLV infections due to higher levels of IL10 and lower CD4 counts." (PMID 19806226, 2009). "The use of such viruses prevents re-infection events and bypasses the natural mode of HIV-1 entry (namely via a CD4- and CCR5-dependent pathway)." (PMID 19419540, 2009). "In CD3/CD28 pre-activated CD4 T cells, both the VSV-G-pseudotyped HIV-1 and the wild-type virus replicated after infection (Figure 5A1 and 5B1)." (PMID 19851458, 2009). "Taken together, these data show that high quality, multi-cytokine producing virus-specific memory CD4+ T cells are generated following CVB3 infection, which differentiate into functional secondary effector T cells upon challenge infection." (PMID 19834548, 2009). "Next, we measured the ex vivo and in vitroproduction of IL-4 by CD4+ T cells in draining lymph nodes of BALB/c and CBA mice two weeks post infection." (PMID 19292771, 2009). "Both the H4 specific CD4 and CD8 T cells were recruited to the site of infection, at the onset of infection." (PMID 19357780, 2009). "We therefore raised CD4+ T cell clones specific for this BHRF1 epitope from a DR4-positive EBV-immune donor and tested these on autologous B cells after infection with the BZKO virus." (PMID 19283066, 2009). "Cells from infected lungs, taken at week 6 or week 43 post infection, were stimulated with TB10.4 3–11 or TB10.4 74–88 prior to staining with anti-CD4, -CD8, -IFN-γ, -TNF-α and –IL-2." (PMID 19529765, 2009). "We, therefore, analyzed autophagy in CD4 T cells and macrophages, the two main target cells of HIV-1, during infection with either X4 or R5 strains." (PMID 19492063, 2009). "The percentage of NK cells, CD4+ and CD8+ T cells recruited to the brain during infection was similar in anti-IP-10-treated and control mice." (PMID 19343215, 2009). "In conclusion, both the vaccine induced CD4 and CD8 T cells undergo cell division and were recruited to the site of infection, at the onset of the infection." (PMID 19357780, 2009). "We also observed that CD4 and CD8 T cells accumulated more rapidly in the lungs of PCN-treated mice following infection than in the lungs of PBS-treated mice." (PMID 19774076, 2009). "In agreement with previous studies, aerosol infection with M.tb induced substantial amounts of TB10.4 specific CD8 and CD4 T cells in the lungs." (PMID 19529765, 2009). "In mice depleted of CD4+ lymphocytes, significant apoptosis of recruited CD8+ and B-lymphocytes is also observed even in the face of progressive infection and tissue inflammation." (PMID 19558669, 2009). "The vaccinated and challenged mice were given BrdU in the drinking water three days before sacrifice to measure the degree of proliferation of CD4 and CD8 T cells at two weeks post infection." (PMID 19357780, 2009). "In order to precise the cellular source of IFN-γ among splenocytes, the intracellular production of this cytokine by splenic NK cells, NKT cells, γδ CD4 and CD8 T cells during infection was analysed by flow cytometry." (PMID 19508725, 2009). "Two weeks post infection we observed a significant higher proportion of Ag85B and in particular of TB10.4 specific CD4 T cells in the lungs in the rH4/Ad-H4 group when compared to the non-vaccinated group (p<0.01)." (PMID 19357780, 2009). "Memory CD4 and CD8 memory cells are less frequent, functionally impaired and target less viral proteins than in patients with resolved infection." (PMID 21994550, 2009). "In this setting, the activated HIV-specific CD4+ T cell, expressing CCR5 and high levels of CD38, are prime targets for infection in vivo during primary HIV-infection, which explains the preferential infection of HIV-1 specific CD4+ T cells." (PMID 19165342, 2009).
infection (continued). "As an internal control, we also tested the same target cells for recognition by CD4+ T cells against another DR4-restricted epitope, this time derived from an antigen known to be expressed early post-infection, EBNA2." (PMID 19283066, 2009). "PBMCs from 373 patients with chronic, untreated clade C infection were stimulated with a pool of HIV-1 clade C Gag peptides and screened for IFN-γ-producing CD4+ T cell responses by intracellular cytokine staining (ICS) assay." (PMID 19352428, 2009). "CXCL-10 initiates its biological functions through binding to its high affinity receptor CXCR-3 leading to recruitment of the activated effector lymphocytes including CD4+ and CD8+ T cells as well as NK cells to the site of infection or injury." (PMID 19442267, 2009). "After the intravenous or intraorgan infection with HIV-1, only human cells were infected and from these, only CD4+ T and myelomonocytic cells." (PMID 19674458, 2009). "Compromised thymic output, and a correlation of CD4 T-cell recovery following ART initiation and thymic volume, has been reported in chronic HIV-1+ infection." (PMID 19434236, 2009). "To validate this finding, we also evaluated the infection frequency by quantitative real time PCR for SIV DNA within sorted populations of naïve and memory CD4+ T cells from samples of spleen collected at necropsy of five of the ND macaques." (PMID 19360097, 2009). "The presence of activated and proliferating CD4+ CCR5+ gag specific T cells, expressing perforin and granzyme B, in early primary infection supports a potential role for them in helping to control viral replication." (PMID 19165342, 2009). "Considering the results obtained with anti-CD4 and anti-CD8 Ab in the ELISPOT assay, the PBMC from PCV2-immune animals, isolated 3 months after infection, were analysed further with respect to their phenotype by flow cytometry." (PMID 20028550, 2009). "Direct tetramer staining showed that the tetramer-bound P65-specific T cells constituted about 0.2–0.3% of CD4 T cells in PBL, lymph nodes, spleens, and lungs at day 63 post-infection." (PMID 19730727, 2009). "Four days post-infection with the PR8 virus, CD4+ T cells in the lungs of both H17-memory and naïve WT and IL-6−/− mice were enumerated by flow cytometry." (PMID 18389078, 2008). "HIV infection is detected in lymphoid tissues and CD4 depletion occurs after HIV infection, but the extent of CD4 depletion can vary widely during infection." (PMID 18237418, 2008). "Cells from transgenic rats expressing human CD4 and CCR5 receptors, as well as the transgenic animals, can support infection by wild-type HIV." (PMID 18575609, 2008). "Since the CXCR4 co-receptor was highly expressed on the surface of the CD8+ T-cells and the affinity of gp120 for the CD4 molecule had already been established, we examined the possibility of CD4 up-regulation on the surface of CD8+ T-cells during infection." (PMID 18923697, 2008). "T-cell analysis showed that at day 3 more of the CD4+ and CD8+ T cells, recruited to the site of infection with vΔC16, were activated (CD69+) compared with controls." (PMID 18796705, 2008). "Later in infection a broadening or switch occurs and HIV evolves to infect cells expressing CD4 and the co-receptor CXCR4 (R4 strains)." (PMID 18312662, 2008). "Reduction in significant amount of CD4, CD8 and CD19 positive cells at 72 h post infection (p < 0.000) was observed in infected mice." (PMID 18937835, 2008). "Within 12 hours after infection of these naïve mice, approximately 2% of the memory SMARTA CD4+ T cells were actively producing IFNγ, but those responding cells showed no CFSE dilution." (PMID 18404208, 2008). "The present analysis of a larger number of SIVsmm infections now reveals a significant correlation between efficient MHC-I downmodulation and stable high CD4+ T cell counts." (PMID 18636106, 2008).
infection (continued). "We used a direct ex vivo antigen presentation assay to probe the capacity of flow cytometrically purified DC populations to drive amplification of CD4+ and CD8+ T cells following infection with influenza virus by different routes." (PMID 18301768, 2008). "While this approach is attractive as it allows for a simultaneous quantitation of CMV specific CD4 and CD8 T cells, it seems more time consuming due to the need of cell purification, generation and infection of dendritic cells, and overnight stimulation." (PMID 18982061, 2008). "Surprisingly, the number of total or activated (CD69+) CD4+ T cells that were elicited to the lungs of RSV infected mice did not change when cDC and pDC or cDC alone were expanded before infection." (PMID 18320041, 2008). "The entry inhibitors specifically block interactions of envelope with CD4 or CCR5, or prevent gp41 conformational changes required for fusion, while monoclonal antibodies sterically inhibit infection by binding conserved envelope sites on virions." (PMID 18205925, 2008). "Infection with NL4-3 reduced the CD4/CD8 ratio in both the CCR5(+) and CCR5(-) subset of CD4(+) T-cells by approximately 75–80% compared to uninfected control cells." (PMID 18452606, 2008). "For the majority of the HIV-infected population, a period of chronic (or clinically latent) infection can last years where the immune system is still able to function despite ongoing HIV replication and depletion of CD4 cells." (PMID 19936197, 2008). "For this purpose, we infected isolated CD4+ T-cells with HIV using spinoculation and added 12 h later the fusion inhibitor enfurvitide which prevents spreading infection." (PMID 18431484, 2008). "CD134-independent FIV infection is mediated by a direct interaction with CXCR4, analogous to infection with CD4-independent strains of HIV." (PMID 18721458, 2008). "During infection, like IL10 and TGF-β, the principal function of CD4+ CD25+ FoxP3+ Treg is the control of intense inflammation, induced at the site of infection, to avoid tissue damage." (PMID 18665224, 2008). "An increase of at least twice as many neutrophils (CD11b+, CD11c−, Ly6G/c+, CD4−, CD8-) was observed as early as 1 day p.i. in all infection groups, compared with neutrophils numbers in PBS-inoculated mice." (PMID 18670648, 2008). "The CD4+ T cell reservoir latent harboring HIV-1 is established very early in infection and it persists throughout the course of infection with apparent replenishment even in individuals undergoing successful HAART therapy." (PMID 18941536, 2008). "Conversely, we demonstrate that populations of adaptive regulatory CD4+ T cells, that are CD25−, Foxp3− and CD127−, and which do not make IFN-γ, IL-4 or IL-17, develop during both PyL and PyNL infections." (PMID 18401464, 2008). "In the in vitro infection model, integrated HIV-1 DNA levels were 1,873,330 copies/107 resting CD4+ T cells, and 16,600 copies/107 resting CD4+ T cells cultured with L-731,988." (PMID 17727722, 2007). "Phenotypes of sequential isolates changed in six animals from CD4-independent-HIGH to CD4-independent-LOW, while isolates from four animals appeared CD4-independent-HIGH both early and late in infection." (PMID 17645788, 2007). "There was also a measurable rise in fluorescence intensity, evident only in the CD4+CD25+ population, over the first 28 days of infection." (PMID 17563918, 2007). "In one P animal a CD4-independent-HIGH and neutralization resistant phenotype appeared already three months after infection and this population became prevalent at late stages in the P/SP group." (PMID 17645788, 2007). "In the MLN, there were significant increases in the proportion of CD4+CD25+ T cells which express CD103, returning to control levels by day 70 of infection; a similar pattern was observed in splenic populations (data not shown)." (PMID 17563918, 2007).